TRPV4 (transient receptor potential cation channel subfamily V member 4)
Diseases named in the same sentence as TRPV4 in open-access papers (continued):
Sharing a sentence is not in itself a finding about the gene and the disease.
melanoma (continued). "It has been verified that the protein expression of TRPV4 in skin-derived melanoma cell lines (A375, Sk-mel-24, Malme-3M) was significantly higher when compared to the normal epidermal cells (HaCaT) in our previous study." (PMID 36499486, 2022). "Since TRPV4 regulated the cell invasion and migration in melanoma, we tried to inhibit the malignancy by expression reduction and activity inhibition of TRPV4." (PMID 36499486, 2022). "Here, we sought to investigate the role of TRPV4 in the process of exocytosis upon agonist stimulation in the A375 cell, which is a human melanoma cell line, as well as in several expression systems." (PMID 35456964, 2022). "Here, we report that activation of TRPV4 induced massive exocytosis in both melanoma A375 cell and heterologous expression systems." (PMID 35456964, 2022). "Our research indicated that melanoma possesses a higher abundance of TRPV4 among multiple cancers and the expression of TRPV4 in skin-derived melanoma cell lines is significantly higher compared to the normal epidermal cells." (PMID 36499486, 2022). "Strong staining for TRPV4 was found in pathological tissues of malignant melanoma patients when compared with normal skin tissues." (PMID 36499486, 2022). "Our results showed that TRPV4-induced cytoskeleton reorganization is critical for melanoma metastasis." (PMID 36499486, 2022). "In the present study, we found that Baicalin inhibited calcium influx induced by TRPV4 activating and inhibiting melanoma cell migration and invasion." (PMID 36499486, 2022). "Overall, these results suggested that TRPV4 regulated melanoma metastasis by inducing cell morphological changes through the Src-cofilin axis." (PMID 36499486, 2022). "In this study, we investigated the expression profiles of ASIC1, ASIC2, TRPV1 and TRPV4 in malignant melanoma (MM), squamous cell carcinoma (SCC), basal cell carcinoma (BCC) and in nevus cell nevi (NCN)." (PMID 34199609, 2021). "Pharmacological TRPV4 stimulation in human melanoma cells and keratinocytes led to necrosis, cell death, and cellular disarrangement." (PMID 34669779, 2021). "The analysis manifested that melanoma cell lines showed a high expression level of TRPV4, of which A375 was the highest in experimental verification." (PMID 32114881, 2020). "Then we chose three melanoma cells lines (A375, Malme-3M, and Skmel-24) with high malignancy and one normal epidermal cell (HaCaT) to test and verify the protein expression of TRPV4." (PMID 32114881, 2020). "And our data highlighted that AKT signaling regulated cell fate of A375 melanoma cells during TRPV4 activation via enhancing AKT phosphorylation." (PMID 30881453, 2019). "Together, our data demonstrated that TRPV4 channel was functionally involved in cell viability for A375 melanoma cells." (PMID 30881453, 2019). "Taken together, here we have demonstrated that TRPV2 and TRPV4 were distributed in human melanoma A2058 and A375 cells as well as melanocytes." (PMID 30881453, 2019). "Our study showed that TRPV4 channels were functionally expressed in human melanoma cell lines and in human keratinocytes." (PMID 29293584, 2018). "Light microscopy showed that TRPV4-activation produced rapid cellular disarrangement, nuclear densification, and detachment of a large fraction of all melanoma cell lines and HaCaT cells." (PMID 29293584, 2018). "The present in-vitro study characterized TRPV4 channels in human melanoma cell lines and keratinocytes and suggests a utility of small molecule TRPV4 activators to impede cell proliferation and survival." (PMID 29293584, 2018). "Together, we proved functional TRPV4 expression in melanoma cells and immortalized human keratinocytes." (PMID 29293584, 2018). "In whole cell patch-clamp experiments in A375 melanoma cells, the TRPV4-opener, GSK1016790A instantaneously evoked large cation currents that reversed at slightly positive potentials (Erev, ≈+4 mV)." (PMID 29293584, 2018).
melanoma (continued). "Indeed, our results show that Xenopus melanophores express multiple and similar TRP channels, including Trpm8,15 Trpa1, Trpv1, Trpv2, and Trpv4, to those detected in mammalian melanocytes and melanoma cells." (PMID 40978134, 2025). "Similarly, TRPV4 activation has been reported to have influence on melanoma cell proliferation and survival." (PMID 40869148, 2025). "Further investigation of the mechanism behind TRPV4 in regulating melanoma metastasis was arranged." (PMID 36499486, 2022). "Additionally, we found that Baicalin inhibits melanoma metastasis by modulating TRPV4-Src-cofilin axis signaling." (PMID 36499486, 2022). "In this study, we investigated the effect of TRPV4 on melanoma metastasis." (PMID 36499486, 2022). "Therefore, activation of TRPV4 via agonist is responsible for the progressive exocytosis response in these as well as A375 melanoma cells." (PMID 35456964, 2022). "Indeed, increased release of exocytosis after TRPV4 agonist stimulation was accompanied with up-regulation of LAMP2 in human melanoma A375 cells." (PMID 35456964, 2022). "The Src-cofilin pathway played a vital role in TRPV4-induced melanoma metastasis." (PMID 36499486, 2022). "However, human melanoma cells of A2058, as well as G361 with low expression of TRPV4, exhibited nearly imperceptible exocytosis." (PMID 35456964, 2022). "Based on these observations, we hypothesized that TRPV4 could have induced cell death by triggering excessive exocytosis in human melanoma." (PMID 35456964, 2022). "However, the biological correlation between TRPV4 and tumor metastasis, as well as the specific role of TRPV4 in malignant melanoma metastasis, is poorly understood." (PMID 36499486, 2022). "Taken together, TRPV4 showed abnormally high functional expression in melanoma cell lines." (PMID 36499486, 2022). "In summary, our findings may have implications for the potential role of TRPV4 in melanoma metastasis." (PMID 36499486, 2022). "Activation of TRPV4 induces exocytosis and ferroptosis in human melanoma cells." (PMID 36072430, 2022). "Thus, our data suggested that TRPV4 mediated exocytosis via Ca2+/CaM/CaMKII signaling pathway in A375 melanoma cells." (PMID 35456964, 2022). "In our present study, TRPV4 agonism induced ferroptosis in melanoma A375 cell may involve in MAPK signaling." (PMID 35456964, 2022). "Our results showed that TRPV4 expression in melanoma cells (HaCaT, A375, Sk-mel-24, Malme-3M) was indeed higher when compared to the normal epidermal cell line (HaCaT), as well as gastric-derived cells (GES-1, AGS, MGC-803, BGC-823) and colorectal-derived cells (NCM460, SW480, SW620, HCT116)." (PMID 36499486, 2022). "Baicalin could decrease melanoma metastasis by regulating cell motility and the mechanism of anti-tumor metastasis is related to blocking TRPV4 activation." (PMID 36499486, 2022). "In this study, we examined the role of TRPV4 in melanoma metastasis." (PMID 36499486, 2022). "In the present study, we have demonstrated that agonist stimulation of TRPV4 strongly evokes exocytosis in A375 melanoma cells, which could be confirmed in multiple expression systems exogenously expressing TRPV4." (PMID 35456964, 2022). "In this study, we aimed to examine the role of TRPV4 in melanoma metastasis through experiments and clinical data analysis, and the underlying anticancer mechanism of Baicalin, a natural compound, and its inhibitory effect on TRPV4 with in vivo and in vitro experiments." (PMID 36499486, 2022). "To determine whether TRPV4 is functionally expressed in melanoma cells, we performed Ca2+ imaging to examine the fluctuation of intracellular Ca2+ after TRPV4 activation." (PMID 36499486, 2022). "Therefore, we screened melanoma cell line A375 which has a high expression level of TRPV4, and studied the cellular temperature change when TRPV4 was activated by GSK1016790A or inhibited by HC067047." (PMID 32114881, 2020). "Is calcium involved in the regulation of functional TRPV4 in melanoma?" (PMID 30881453, 2019).
melanoma (continued). "Thus, AKT functioned as downstream effectors for calcium signaling mediated by TRPV4 in human A375 melanoma cells." (PMID 30881453, 2019). "Furthermore, TRPV4 mediated cell apoptosis of melanoma via phosphorylation of AKT and was involved in calcium regulation." (PMID 30881453, 2019). "Here our study provides new insight as we could show that pharmacological activation of TRPV4 considerably impaired melanoma cell survival and proliferation." (PMID 29293584, 2018). "Pharmacological targeting of TRPV4 could be an alternative or adjuvant therapeutic strategy to treat melanoma progression and other proliferative skin disorders." (PMID 29293584, 2018). "Together, this suggested that pharmacological TRPV4 activators could have utility as inhibitors of melanoma growth and disease progression and possibly other proliferative skin conditions." (PMID 29293584, 2018). "To determine if activation of TRPV4 has any detrimental effects on A375 melanoma cells, we next tested whether TRPV4-activation produced alterations in cell morphology and monitored alive A375 cells under a light microscope over 60 min." (PMID 29293584, 2018). "A major goal of the present study was to determine whether pharmacological manipulation of TRPV4 has any consequences for melanoma cell survival and/or proliferation." (PMID 29293584, 2018). "Here, we hypothesized that TRPV4 is expressed in human melanoma and that pharmacological activation interferes with cell proliferation." (PMID 29293584, 2018). "In summary, it seems to be clear that TRPV4 activation in A375 cells produced substantial cytotoxicity and it is therefore worth speculating that the cytotoxicity of this or other TRPV4 activators could help to impede melanoma progression and metastasis." (PMID 29293584, 2018). "In the present study, we tested the hypothesis that 1) TRPV4 is functionally expressed 5 and that 2) pharmacological manipulation of TRPV4 interferes with melanoma cell proliferation." (PMID 29293584, 2018). "In conclusion, our study described expression and function of TRPV4 (and KCa3.1) channels in melanoma cells and revealed a potential utility of TRPV4-activators as alternative or adjuvant therapeutic strategy to produce melanoma cell death and to impede tumor progression." (PMID 29293584, 2018). "Therefore, it is urgent to investigate the role of TRPV4 in melanoma metastasis." (PMID 36499486, 2022). "Thus, our results showed that Ca2+-permeable TRPV4 is functionally and aberrantly expressed in melanoma cell lines, and its activation could be inhibited by Baicalin treatment." (PMID 36499486, 2022). "We hypothesized that Baicalin could inhibit melanoma metastasis in a TRPV4-dependent manner." (PMID 36499486, 2022). "Moreover, activation of TRPV2 and TRPV4 could lead to the decline of cell viability for melanoma A2058 and A375 cells." (PMID 30881453, 2019). "Interestingly, 2-APB application dominated A2058 cells undergoing necrosis and late apoptosis other than early apoptosis both via FITC-Annexin V/PI staining and Hochest33342/PI staining, which was clearly different from the activation of TRPV4 in melanoma A375 cells." (PMID 30881453, 2019). "Considering TRPV4 a thermosensitive channel, it might be worth testing the impact of TRPV4 activation in combination with radiotherapy to enhance the latter’s efficacy, particularly in pigmented melanoma lines." (PMID 29293584, 2018). "This review highlights the physiological expression of key TRP subfamilies (TRPM1, TRPM7, TRPM8, TRPV1, TRPV4, and TRPM2) in melanocytes and discusses their dysregulation in melanoma cells." (PMID 40869148, 2025). "Among the oncogenic TRP isoforms, TRPM7, TRPV1, TRPV4, and TRPM8 have received considerable attention due to their frequent overexpression in melanoma cells and their functional contributions to the malignant phenotype." (PMID 40869148, 2025).
melanoma (continued). "In the context of melanoma, several TRP channel subtypes, including TRPM1, TRPM7, TRPV1, and TRPV4, have been shown to be differentially expressed and functionally active in tumor cells." (PMID 40869148, 2025). "Brain extracellular ion concentrations (Ca2+, K+, glutamate) also drive patterned electrical activity in melanoma cells via ORAI1-STIM1 store-operated entry and TRPM7/TRPV4 mechanosensitive channels." (PMID 41463339, 2025). "Plateau phases in melanoma cells are produced by STIM1/ORAI1 store-operated Ca2+ entry and mechanosensitive TRPM7/TRPV4 channels, which transform perivascular forces and osmotic conditions into electrical signals." (PMID 41463339, 2025). "To exclude the possibility of the specific effect of Baicalin in human melanoma cell lines, we performed the in vivo metastasis experiment in C57BL6 using B16F10, which also expresses TRPV4." (PMID 36499486, 2022). "In this study, we investigate the expressions of ASIC1, ASIC2, TRPV1 and TRPV4 in squamous cell carcinoma (SCC), basal cell carcinoma (BCC), malignant melanoma (MM) and in nevus cell nevi (NCN)." (PMID 34199609, 2021). "The mRNA expression of TRPV4 in cells from various sources were analyzed on the basis of CCLE database and melanoma cells displayed the highest expression for TRPV4." (PMID 32114881, 2020). "Overall, our studies revealed that TRPV4 and TRPV2 mediated melanoma cell death via channel activation and characterized the mechanism of functional TRPV4 ion channel in regulating AKT pathway driven antitumor process." (PMID 30881453, 2019). "Due to the significant upregulation of TRPV4 which has been detected in melanoma A375 cells, GSK1016790A, a selective activator of TRPV4, has been applied to A375 cells as well as melanocytes." (PMID 30881453, 2019). "Whether TRPV4 is also mechanistically implicated in melanoma cell proliferation is not clear." (PMID 29293584, 2018). "The apparent and immediate cytotoxicity of TRPV4-activation was not limited to A375 since the other melanoma lines, MKTBR and SK-MEL-28, responded similarly to TRPV4-activaton within the first hour." (PMID 29293584, 2018). "In contrast, low expression level of TRPV4 has been reported in the keratinocytes of non-melanoma skin cancer patients, and TRPV4 activation in melanoma cells resulted in increased exocytosis and ferroptosis rates." (PMID 36619170, 2022). "Meanwhile, 2-APB, an activator of TRPV2 (also activates TRPV1 and TRPV3 but does not affect TRPV4), clearly attenuated the proliferation of A2058 melanoma cells (IC50 = 150 μM)." (PMID 30881453, 2019). "We demonstrated TRPV4 gene expression and TRPV4 channel membrane function in melanoma cell lines and non-cancer HaCaT keratinocytes." (PMID 29293584, 2018). "Concerning the other two melanotic melanoma lines, MKTBR and SK-MEL-28, we measured similar TRPV4 currents and found similar expression levels for TRPV4 channels while KCa3.1 expression appeared to lower to some degree in MKTBR and SK-MEL-2 if compared to A375 cells." (PMID 29293584, 2018). "Given that pharmacological activation of TRPV4 could inhibit cell viability, to assess the lethality of GSK1016790A to melanoma cell lines, A375 cells were treated with GSK1016790A at various concentrations for 24 h and then analysed by flow cytometry with FITC conjugated Annexin V and PI." (PMID 30881453, 2019). "TRPV4 functions were studied in melanoma cell lines (A375, SK-MEL-28, MKTBR), immortalized non-cancer keratinocytes (HaCaT), and murine 3T3 fibroblasts by patch-clamp, qRT-PCR, intracellular calcium measurements, cell proliferation, and flow cytometric assays of apoptosis and cell cycle." (PMID 29293584, 2018).
diabetes (18 papers, 2007 to 2024). "In both humans and laboratory animals, TRPV4 stimulation leads to complications associated with diabetes." (PMID 38976129, 2024). "Subsequently, Dias and collaborators (2019) investigated TRPV4 expression and its association with mechanical and cold allodynia in streptozotocin-induced diabetes in mice." (PMID 36670886, 2022). "Taken together, these findings strongly indicate that downregulation of TRPV4 expression contributes to the endothelial dysfunction associated with diabetes." (PMID 34616307, 2021). "The exact underlying mechanism needs to be clarified, but the fact that TRPV4 deletion prevents retinal edema formation associated with diabetes argues in favor of TRPV4 as an etiological agent for DME." (PMID 31048895, 2019). "An additional confounding aspect is that diabetes or hyperglucemic-mimicking conditions were associated with TRPV4 down-regulation in different cell types, including rat retinal microvascular endothelium, mesenteric artery endothelial cells, and human collecting duct cells." (PMID 31048895, 2019). "TRPV4 inhibitors resolve the BRB breakdown associated with streptozotocin-induced diabetes." (PMID 29026201, 2017). "Taken together, these data suggest that vasoinhibins may block excessive BRB permeability associated with diabetes by inhibiting TRPV4." (PMID 29026201, 2017). "Given that TRPV4 signalling has been demonstrated to play a role in several types of endothelium-dependent vasodilatation, it is tempting to speculate that loss of TRPV4 function may contribute to endothelial dysfunction in diabetes." (PMID 26047504, 2015). "Reduced TRPV4 channel expression has been suggested as an underlying reason for the dysfunction of vascular function during diabetes, but it may be a compensatory effect in diabetes." (PMID 29026201, 2017). "In the mitochondria of DRGs, the glucose oxidation brought on by diabetes mellitus (STZ) causes an intracellular free Ca2+ and Zn2+ influx excess that is dependent on TRPV4." (PMID 38976129, 2024). "An overview of how resveratrol (RESV) inhibits TRPV4 in mice to modulate the effects of diabetes mellitus-induced diabetic peripheral neuropathy (DPN)." (PMID 38976129, 2024). "The TRPV4 role has been researched in models that induce neuropathic pain, such as trauma, surgery, chemotherapy, diabetes and alcohol intake." (PMID 36670886, 2022). "It was shown that TRPV4 upregulation in diabetes induced rat cardiac fibroblasts and pharmacological treatment with TRPV4 antagonist reduced cardiac fibrosis in streptozotocin induced diabetic rat model." (PMID 34831281, 2021). "In relation to diabetes, high glucose downregulated the protein expression of TRPV4 channels, thereby attenuating the agonist-stimulated Ca2+ influx in retinal microvascular endothelial cells." (PMID 31370156, 2019). "Rodent experiments support our observations by showing TRPV4 downregulation in streptozotocin-induced diabetes." (PMID 31481433, 2019). "Transient receptor potential cation channel subfamily vanilloid member 4 (TRPV4) plays an intricate role in homeostatic processes that needs to be deciphered in normal and diabetic retina." (PMID 31048895, 2019). "In this study, we first analyzed retinas of Trpv4-/- mice subjected to 4 weeks of experimental diabetes induced by streptozotocin." (PMID 31048895, 2019). "Our data further suggest that TRPV4 participates in the effect of diabetes on retinal fluid accumulation." (PMID 31048895, 2019). "For instance, the decreased level of TRPV4 induced by hyperglycemia and diabetes contributes to diabetes-induced endothelial dysfunction and retinopathy in retinal microvascular endothelium." (PMID 29433476, 2018). "We showed that TRPV4 antagonism and vasoinhibins synergize by activating complementary pathways to counteract the diabetes-like effects on RPE permeability." (PMID 29026201, 2017). "This further indicates that after 4 weeks of diabetes or high glucose, some TRPV4 is still functional." (PMID 29026201, 2017).